AR (androgen receptor)
Diseases named in the same sentence as AR in open-access papers (continued):
Sharing a sentence is not in itself a finding about the gene and the disease.
glioma (continued). "Furthermore, AR expression was more frequent in MGMT-unmethylated gliomas compared with MGMT-methylated tumors (p = 0.02)." (PMID 41153666, 2025). "AR overexpression has been observed in gliomas and their stem-like cell compartments, supporting the idea that AR signaling may affect the development of brain tumors." (PMID 41153666, 2025). "We also performed a DNA methylation analysis of the AR and its co-regulatory genes to investigate whether epigenetic mechanisms might regulate AR expression, observing some differences in different classes of gliomas." (PMID 41153666, 2025). "The data of the present study suggest that gender differences in glioma patients are significant and could be attributed to the role of AR expression, which is controlled by DNA methylation and X-chromosome aneuploidy." (PMID 41153666, 2025). "Additionally, methylation patterns of AR co-regulators located on the X chromosome suggest epigenetic regulation of AR signaling in gliomas." (PMID 41153666, 2025). "Moreover, AR expression was more frequent in MGMT-unmethylated gliomas compared with MGMT-methylated tumors (p = 0.02)." (PMID 41153666, 2025). "In our analysis AR expression was correlated with gender and with glioma grade." (PMID 41153666, 2025). "Recent research suggests a role for the AR in gliomagenesis; however, the expression level of the AR, its regulatory mechanisms, and its prognostic significance in gliomas remain unknown." (PMID 41153666, 2025). "The results shown here can be potentially interesting as the AR could be a therapeutically useful target for glioma treatment." (PMID 41153666, 2025). "In our series AR expression positively correlated with glioma grading and with gender." (PMID 41153666, 2025). "Still only BMP2, MMP13, MMP2, LCK, MMP9, and AR have been reported to affect the glioma invasion." (PMID 39458959, 2024). "When considering the rate, inheritance pattern, and population frequencies of detected rare, damaging coding variants in MYO10, AR and GALNT13, enhancer-linked risk variant in CCDC26, and other detected risk variants, our results suggest polygenic inheritance of familial glioma in Finland." (PMID 38773237, 2024). "Similarly, the decreased SVIP expression, as well as increased AR expression, in glioma tissues correlated with gliomas progressing from low to high grades." (PMID 37408196, 2023). "We also demonstrated that AR protein expression could be detected in glial tumors in real time by positron emission tomography/computed tomography scanning using [F18] DHT." (PMID 38203506, 2023). "In gliomas, many cuproptosis‐related genes could activate the androgen receptor, cell cycle, DNA damage response, and PI3K/AKT signaling pathways and inhibit TSC/mTOR and EMT signals." (PMID 37515314, 2023). "This indicates a potential role of sex receptors in glioma tumors (such as the androgen receptor)." (PMID 36361793, 2022). "In their work, the authors used imaging to identify AR-positive gliomas." (PMID 36361793, 2022). "These could be species‐specific effects, however, AR blockade in glioma cancer stem cells has been shown to decrease proliferation and downregulate markers related to stemness, making AR an even more interesting treatment target in GBM." (PMID 35661403, 2022). "Both of PGR and AR have been reported to play important roles in glioma." (PMID 35120529, 2022). "Nonetheless, the particular efficacy of AR blockade in suppressing glioma CSCs signify the importance of further research on this novel target with its potential to overcome the tumor resistance mediated by CSCs to current standard care with RT and/or chemotherapy." (PMID 34094902, 2021).
glioma (continued). "Interestingly, AR expression was also present in 39% of the female glioma samples, similar to the detectable ratio in male (47%)." (PMID 34094902, 2021). "Based on these results, we hypothesize that glioma CSCs may be more dependent on AR expression/functions for maintenance and/or survival than more differentiated tumor cells." (PMID 34094902, 2021). "We recently showed that AR protein expression could be detected in glial tumors in real time by positron emission tomography/computed tomography scanning 16β-18F-fluoro-5α-dihydrotestosterone." (PMID 34681618, 2021). "From a functional point of view, AR seemed to promote tumor growth in glioma: an increase in cell death and an accumulation of cells in sub-G1 are observed when blocking the AR activity by specific inhibitors (bicalutamide or enzalutamide) or protein expression by siRNA in A172, U87 and T98G cells." (PMID 33266110, 2020). "Interestingly, the broad set-up of our t/RNA-NGS assay allowed the frequent detection of androgen receptor (AR) in gliomas at relatively high levels." (PMID 31747973, 2019). "Further analysis of AR RNA amplification from several datasets, including the TCGA dataset, with OncomineTM software (Compendia Bioscience, Ann Arbor, MI, USA), validated the RNA results and showed that AR-RNA is overexpressed also in low-grade gliomas." (PMID 29731997, 2018). "If the growth of glioma cells relied on AR signaling pathway, it could be delayed with an appropriate AR antagonist and vice versa." (PMID 28423563, 2017). "Furthermore, it has been proved that SVIP is down-regulated as well as AR is up-regulated in glioma cell lines with R1881 treatment." (PMID 28423563, 2017). "In order to investigate whether AR signaling plays a role in the pathogenesis of glioma, firstly we checked the AR protein expression in 11 tumor cell lines, mouse and rat brain tissue." (PMID 28423563, 2017). "Furthermore, the expression level of AR, analyzed by WB and IHC, in tumor tissue was closely correlated with the malignancy of glioma, whereas SVIP protein expression showed an opposite trend." (PMID 28423563, 2017). "Moreover, the AR expression is increased while SVIP expression is decreased in tumor tissue of glioma patients, which is in agreement with the progressing WHO grades." (PMID 28423563, 2017). "RNA-Seq and TCGA analyses delineated AR-associated regulatory networks, while integrated cellular and molecular approaches utilizing human and mouse GBM cell lines, as well as in patient-derived primary high-grade glioma cultures, interrogated signaling and immune paradigms." (PMID 41674836, 2026). "Furthermore, glioma tissues often display heightened expression of the AR." (PMID 40075208, 2025). "Also, an association between AR expression and glioma grade progression has been observed irrespective of biological sex." (PMID 40399259, 2025). "Additionally, glioma U87 cells were shown to produce ligands necessary for AR activation." (PMID 36361793, 2022). "However, there are no published studies regarding the interplay between EGFR and AR in gliomas." (PMID 34681618, 2021). "Androgen receptor signaling pathways in gliomas remain largly unknown." (PMID 29731997, 2018).
glioma (continued). "Furthermore, to investigate whether AR antagonist could inhibit glioma growth in vivo, flank tumor xenograft model bearing U87 cells was treated with MDV3100 or placebo (vehicle control) by daily oral gavage." (PMID 28423563, 2017). "However, AR signaling may aggravate gliomas, and the safety of using DHT in GBM patients is uncertain." (PMID 27542970, 2016). "In our series, AR CAG repeats and “Intra CAG-CGG repeats” regions resulted hypermethylated in gliomas with low AR protein levels, as well as in LGGs." (PMID 41153666, 2025). "In particular, we assessed the methylation pattern of the AR gene and its regulatory genes such as FLNA, UXT, and MAGE family members, and analyzed X-chromosome copy number variations in a series of gliomas." (PMID 41153666, 2025). "In males, AR CAG repeats and AR INTRA CAG-CGG repeats resulted hypomethylated in AR-positive gliomas." (PMID 41153666, 2025). "The effects of BMP2 and AR on glioma reported in the literature are consistent with the results of this study showing that BMP2 and AR are protective factors in glioma patients." (PMID 39458959, 2024). "Our results indicate that the role of AR and SVIP in the pathogenesis of different types (subtypes) of gliomas requires being defined discretely." (PMID 28423563, 2017). "A 95% downregulation of SVIP expression, from NC to high-grade gliomas (WHO III and IV) was observed; consecutively, the AR expression increased as the tumor grade progressed, irrespective of the gender." (PMID 28423563, 2017). "AR nuclear expression, in addition, seems to have a close correlation with glioma grading, being more expressed in GBM IDH-wt, and appears to influence the prognosis of gliomas, reducing survival." (PMID 41153666, 2025). "To further explore the specific molecular mechanism of this phenomenon, we assessed four transcription factors of Galectin-9 (AR, CEBPA, CEBPB, and TFAP2C) and found that CEBPA on chromosome 19q played a leading role in the transcriptional regulation of Galectin-9 in gliomas." (PMID 34956239, 2021). "The results strongly suggest that AR may be involved in the process of gliomagenesis and act as an essential factor for glioma CSC maintenance and/or proliferation, which is consistent with the findings that androgen/AR promotes neural stem cell proliferation." (PMID 34094902, 2021). "The first immunohistochemical analysis of low-grade and high-grade gliomas showed that AR protein expression level neither depended on tumor grade nor was a reliable indication for patient survival." (PMID 33266110, 2020). "We found that AR expressed in the glioma cell lines, neuroblastoma cells, and neurons but not in glial cells." (PMID 28423563, 2017). "Thus, in the current study, AR and SVIP expression in each grade glioma tissue are mostly compared with normal tissues, instead of peritumoral tissues." (PMID 28423563, 2017). "Although no previous studies have suggested direct associations between genes, including AR and PRKCA or pathways in cancer, gliomas, ErbB signaling pathway, and CTEPH, they led to our hypothesis that AR, PRKCA, and pathways in cancer, gliomas, and ErbB signaling pathway are associated with CTEPH." (PMID 28904974, 2017). "The association between AR expression and patients' survival was previously studied in TCGA datasets, where high AR mRNA and protein expression was a negative prognostic factor in low‐grade glioma, a finding we could not confirm when analysing IDH mutated glioma." (PMID 35661403, 2022).
lymph node metastasis (37 papers, 2012 to 2026). "In invasive breast carcinoma (NST), low AR staining was associated with high tumor stage (p < 0.0001), high tumor grade (p < 0.0001), lymph node metastasis (p < 0.0001), and shorter overall survival (p = 0.0094)." (PMID 38790919, 2024). "Cumulatively, a high malignancy grade and the presence of lymph node metastases were associated with a lower AR expression in the PCa‐associated stroma." (PMID 29808619, 2018). "Kraby and colleagues reported discordant data on AR expression between primary tumor and correspondent lymph node metastases, observed in 21.4% of cases and often associated with a switch in AR status from negative primary tumor to positive axillary lymph node metastasis." (PMID 36111296, 2022). "AR overexpression was associated with longer disease-free interval, overall survival, and cancer-specific survival by univariate and multivariate survival analyses, independently of clinical stage at diagnosis (tumor size, lymph node metastasis, distant metastasis)." (PMID 31888566, 2019). "On the contrary, the LNCaP line (derived from lymph node metastasis) is AR- and PSA-expressing, being an androgen-dependent adenocarcinoma, with clinical behavior in most of the encountered PC cases." (PMID 41225814, 2025). "A total of 113 patients were positive for lymph node metastasis (pretreatment) (71.1%), 46.5% were ER positive, 34.0% were PgR positive, and 40.3% were over 80% AR positive." (PMID 35663978, 2022). "A study on androgen receptor (AR) overexpression increased blood metastasis but reduced LMs showed that there was also a gender difference between lung metastasis and lymph node metastasis in RCC patients." (PMID 35480102, 2022). "Studies investigating the correlation between AR expression and lymph node metastasis are highly discordant." (PMID 33915941, 2021). "Lymph node metastasis was significantly more frequent in the LAR subtype, and there was a statistical association between AR-positive TNBC and lymph node metastases." (PMID 33915941, 2021). "Expression of AR correlated with lower grade (P < 0.001) and conferred a favorable prognostic significance in patients with axillary lymph node metastasis (P = 0.005)." (PMID 32850312, 2020). "ERβ1 expression was negatively correlated with ZEB1 expression and lymph node metastasis, and positively correlated with the expression of AR and E-cadherin." (PMID 28583190, 2017). "LAPC-4 cells were also derived from a patient lymph node metastasis, but they express wild-type AR and are reliant on exogenous androgen to thrive in culture." (PMID 27036029, 2016). "A recent microarray analysis on patient tissues revealed that strong AR expression was detected in benign prostate (83%), localized prostate cancer (100%), and lymph node metastasis (80%), but less (40%) in metastatic hormone-resistant prostate cancer." (PMID 23041906, 2012). "Yet, AR positivity was significantly associated with post-NACT axillary lymph node metastasis (p = 0.017), and the complete axillary response was significantly more prevalent in AR-negative patients (p = 0.002)." (PMID 41800049, 2026). "Lymph node metastases were more common in AR+/NE+ (29%) than other subtypes (9%–11%)." (PMID 40493417, 2025). "Within the 189 cases, AR- cases were positively correlated with higher T stage (86.1 vs. 40.5%, P < 0.001, chi-square test), lymph node metastasis rate (69.4 vs. 24.2%, P < 0.001, chi-square test), and distant metastasis rate (63.9 vs. 19.6%, P < 0.001, chi-square test) than AR+ cases." (PMID 36033483, 2022). "Moreover, ERβ1 expression was negatively correlated with lymph node metastasis (r = −0.368, P = 0.001), and positively correlated with the expression of AR (r = 0.309, P = 0.005)." (PMID 28583190, 2017). "Here we report that there is also a gender difference between pulmonary metastasis and lymph node metastasis showing that the androgen receptor (AR)-positive ccRCC may prefer to metastasize to lung rather than to lymph nodes." (PMID 29030639, 2017).
lymph node metastasis (continued). "No consistent association of AR expression with differentiation, lymph node metastasis, and ECOG performance status was observed." (PMID 29108248, 2017). "In addition to tumor size, lymph node metastasis, nuclear grade, HER2 status, and Ki67 index, AR expression was found to be significantly associated with DFS by univariate analysis." (PMID 24403250, 2013). "A lower percentage of AR‐positive PCa‐associated stroma nuclei was observed in the primary tumors of patients with lymph node negative disease as compared to patients with pelvic lymph node metastases." (PMID 29808619, 2018). "Moreover, PD-L1 overexpression was statistically significantly linked to high Gleason scores and positive androgen receptor of PCa, while it was also associated with age, pathologic stage, lymph node metastasis and preoperative PSA level but with no statistical significance." (PMID 30733677, 2018). "When compared to AR-TNBC, AR+TNBC were larger and more frequent in older women, showed a higher incidence of apocrine differentiation, a higher incidence of axillary lymph node metastasis, and lower proliferation rates." (PMID 29883487, 2018). "High expression of AR was significantly correlated with the grade, but not with myometrial invasion, lymph node metastasis, or distant site metastasis." (PMID 38890503, 2024). "Similarly, the expression of AR was found commonly in lymph node metastatic TNBC, but rarely in non-lymph node metastatic tumors." (PMID 35053220, 2022). "At the 1% cutpoint AR positive (AR+) tumors were significantly larger and showed a higher incidence of lymph node metastasis than AR negative (AR-) tumors." (PMID 29883487, 2018). "Additionally, PD-L1 has a statistically significant correlation with Gleason score and androgen receptor status, while the correlations with age, pathologic stage, lymph node metastasis, and preoperative PSA level were not statistically significant." (PMID 30733677, 2018). "Univariate analysis showed that no lymph node metastasis (P = 0.013), higher histological grade (P = 0.009), HER2 IHC 0 (P = 0.013) and AR negative (P = 0.015) were more likely to achieve pCR after neoadjuvant therapy." (PMID 37099044, 2023). "A meta-analysis involving 2826 TNBC patients revealed AR expression was related to better DFS and lower tumor grade, but a higher incidence of lymph node metastasis, and no impact on OS." (PMID 35053220, 2022).